TNNI3 (troponin I3, cardiac type)
Description:
Troponin I is the inhibitory subunit of troponin, the thin filament regulatory complex which confers calcium-sensitivity to striated muscle actomyosin ATPase activity.
Synonyms: TNNC1; CMH7; cTNI; CMD1FF; CMD2A; RCM1
Tractability: Small molecule: a drug acting on it is in phase 2 or 3 trials; a structure with a bound ligand is known; a high-quality ligand is known; it belongs to a druggable protein family. PROTAC: a small molecule that binds it is known.
Gene: Protein-coding gene on chromosome 19 (55,151,767 to 55,157,773, reverse strand). Ensembl gene ENSG00000129991.
Subcellular location (Human Protein Atlas): Cytosol; Vesicles
Pathways (Reactome):
Muscle contraction: Ion homeostasis; Striated Muscle Contraction
Gene Ontology:
Molecular function: actin binding; actin filament binding; calcium channel inhibitor activity; calcium-dependent protein binding; protein binding; protein domain specific binding; protein kinase binding; troponin C binding; troponin T binding
Biological process: cardiac muscle contraction; heart contraction; negative regulation of ATP-dependent activity; regulation of cardiac muscle contraction by calcium ion signaling; ventricular cardiac muscle tissue morphogenesis; heart development; intracellular calcium ion homeostasis; muscle filament sliding; regulation of systemic arterial blood pressure by ischemic conditions; skeletal muscle contraction; vasculogenesis; regulation of smooth muscle contraction
Cellular component: cardiac myofibril; cardiac Troponin complex; troponin complex; cytosol; sarcomere; contractile muscle fiber; cytoplasm; myofibril
Genetic constraint (gnomAD): Loss-of-function variants: 23 observed, 29.65 expected, observed/expected ratio (o/e) 0.78, 90% interval 0.56 to 1.1. The upper end of that interval is the gene's LOEUF score, 1.1, which puts it in group 4 of 6, group 1 being the genes least tolerant of losing a copy. Missense variants: 236 observed, 272.51 expected, observed/expected ratio (o/e) 0.87, 90% interval 0.78 to 0.96. Synonymous variants: 120 observed, 105.22 expected, observed/expected ratio (o/e) 1.14, 90% interval 0.98 to 1.33.
Gene-disease validity (ClinGen):
ClinGen rates the evidence that TNNI3 causes each of these diseases.
hypertrophic cardiomyopathy (autosomal dominant): Definitive. A condition in which the myocardium is hypertrophied without an obvious cause.
dilated cardiomyopathy 1FF (autosomal dominant): Strong.
dilated cardiomyopathy 2A (autosomal recessive): Strong.
arrhythmogenic right ventricular cardiomyopathy (autosomal dominant): No Known Disease Relationship.
Homologues: Orthologues: guinea pig TNNI3 (94% identical), mouse Tnni3 (93% identical), rat Tnni3 (91% identical), pig TNNI3 (87% identical), tropical clawed frog tnni3 (70% identical), chimpanzee TNNI3 (60% identical), Caenorhabditis elegans unc-27 (29% identical), Caenorhabditis elegans tni-1 (27% identical), Drosophila melanogaster wupA (27% identical), Caenorhabditis elegans tni-3 (26% identical), Caenorhabditis elegans tni-4 (25% identical). Paralogues in human: TNNI1 (52% identical), TNNI2 (47% identical).
Diseases named in the same sentence as TNNI3 in open-access papers:
TNNI3 is named in the same sentence as 344 diseases in open-access papers, as found by Europe PMC text mining. Sharing a sentence is not in itself a finding about the gene and the disease. The quoted sentences say what the papers report.
myocardial infarction (462 papers, 2008 to 2026). Gross necrosis of the myocardium, as a result of interruption of the blood supply to the area, as in coronary thrombosis. "Cardiac troponin I (cTnI), encoded by the TNNI3 gene, is a highly specific marker of myocardial injury, including acute myocardial infarction." (PMID 39772209, 2024). "Troponins I (encoded by TNNI3) is integral to cardiac muscle contraction, which is also used as diagnostic and prognostic indicators in the management of myocardial infarction and acute coronary syndrome." (PMID 31607935, 2019). "We found the elevated cardiac troponin expression (TNNT2, TNNI3, TTN) in cardiomyocytes across various CHD subtypes, suggesting increased myocardial stress and potential heart attack risk." (PMID 41010342, 2025). "Myocardial infarction remains one of the largest causes of death and although rapid ELISA tests against cardiac troponins TNNT2 and TNNI3 play a crucial role, further improvements in diagnosis would be of great clinical benefit." (PMID 29133944, 2017). "The troponin genes (TNNC1, TNNT2, TNNI3), the creatine kinase gene (CKM), and the brain natriuretic peptide gene (NPPA) are recognized biomarkers of myocardial infarction." (PMID 40433126, 2025). "Elevated blood levels of cardiac troponin (cTn), of the cTnI and cTnT subtypes (also known as TNNI3 and TNNT2, respectively), indicate cardiomyocyte injury and cell death, and are used in the clinic as an indicator of myocardial infarction." (PMID 39912384, 2025).
COVID-19 (168 papers, 2020 to 2025). A disease caused by infection with severe acute respiratory syndrome coronavirus 2. "As per univariate and multivariate prognostic analyses, a few important genes, including ALPL, ANGPT2, CD4, G6PD, SERPINE1 and TNNI3, may serve as independent prognostic factors for HCC patients with COVID-19." (PMID 36275701, 2022).
heart failure (143 papers, 2012 to 2026). Inability of the heart to pump blood at an adequate rate to meet tissue metabolic requirements. "Thin filament mutations associated with HCM are predominantly located in TPM1 (α-tropomyosin), TNNT2 (TnT), TNNI3 (TnI), and ACTC1, resulting in a phenotypically distinct class of patients with increased risks for cardiac dysfunction and heart failure." (PMID 34745372, 2021). "At the level of the cardiac sarcomere, as cTnI (TNNI3 gene product) progressively replaces ssTnI (TNNI1) during maturation, there is no reactivation of the fetal TNNI1 gene program, even in disease states including stress, hypertrophy (physiological or maladaptive), ischemia, or in heart failure." (PMID 25358788, 2014).
diabetes (118 papers, 2005 to 2025). "The results of this research may help explain the induction of tacrolimus-induced posttransplantation diabetes mellitus via the low expression of muscle genes including Tpm3, Tnnc1, Tnnt1, Tnni3, Hrh3, Apln, S1pr3, and Cxcl12." (PMID 31998808, 2020).
myocarditis (89 papers, 2007 to 2026). Myocarditis is a condition that is characterized by inflammation of the heart muscle (myocardium). "The incidence of potentially harmful mutations in the genes DSP, PKP2, and TNNI3 (encoding, respectively, desmoplakin, plakophilin-2, and troponin I type 3) is elevated in children with acute myocarditis." (PMID 37456487, 2023). "The critical role of genetic (L)P variants in DSP and TNNI3 was replicated in several studies involving children or adults with myocarditis." (PMID 35877578, 2022). "Homozygous variants in CMP disease genes such as desmoplakin (DSP) and troponin I3 (TNNI3) were identified in pediatric patients with myocarditis." (PMID 35877578, 2022).
cardiomyopathy (83 papers, 2008 to 2026). A disease of the heart muscle or myocardium proper. "Under normal conditions, cardiac contraction genes showed minimal changes, but 12-h fasting disrupted Tnni3 and Myh7 expression (linked to cardiomyopathies), which was prevented by rhFGF21 replenishment." (PMID 40998786, 2025). "Of transcripts associated with cardiomyopathy, hypertrophy, and left ventricle alterations, Q‐PCR analysis was used to monitor the modulation of Ndufb7, Tnnt2, Ttn, Tnni3, and Plag2a." (PMID 37960940, 2023). "The mutation-hotspots of TNNI3 suggest the site of mutation is highly important in cTnI-associated cardiomyopathies, as a disproportionate number of disease-causing mutations occur in the highly conserved regions responsible for interaction between sarcomeric subunits." (PMID 36158814, 2022). "In the sarcomeric group, 3 patients had a variant of unknown significance (2 MYH7 and 1 TNNI3); therefore, the cardiomyopathy in these patients might have been affected by other variables that we have currently not yet identified." (PMID 33605084, 2021). "The study also revealed the possible heterogeneity of TNNI3 mutations across ethnic and geographic backgrounds, suggesting that long-term studies of genetic mutations should be strengthened in the future to promote the development of precision treatment strategies for cardiomyopathy." (PMID 39635265, 2024). "Only two parents with pathogenic variants in the TNNI3 and MYH3 gene, had clinical manifestations consistent with cardiomyopathy and multiple pterygium syndrome, respectively." (PMID 41256177, 2025). "Seven variants (41%) were detected in genes associated with cardiomyopathies including CSRP3, LAMA4, MYH6, MYBPC3, TNNI3, TNNI3K, and TNNT2." (PMID 39272661, 2024). "In the core cardiomyopathy panel, we also identified the missense VUS c.278T>C in the dominant TNNI3 gene, which encodes for the cardiac isoform of troponin I (transcript levels are 720-fold higher in cardiac than in skeletal muscle)." (PMID 39063061, 2024). "All genes encoding the cardiac troponin subunits are targets for cardiomyopathy inducing mutations, whereby TNNI3, encoding cTnI, is the main target for RCM mutations." (PMID 34502534, 2021).
cardiomyopathy (continued). "Some genes are specific to one class of cardiomyopathy like RBM20 in DCM, whereas others like MYPN and TNNI3 are implicated in at least 3 different types of cardiomyopathy." (PMID 30764827, 2019). "As there is no comprehensive study on Indian population, we have analysed all the exons and the exon-intron boundries of TNNI3 gene of Indian cardiomyopathy patients to assign its role in the etiology of cardiomyopathy among Indian populations." (PMID 22876777, 2012). "Overall, recessive TNNI3 protein truncation causes severe pediatric RCM, suggesting that the allelic status, type of genetic alteration, and length of TNNI3 protein truncation determine cardiomyopathy onset and subtype manifestation." (PMID 41918167, 2026). "In April 2024, the ClinGen Cardiomyopathy Variant Curation Expert Panel (VCEP) adapted the ACMG/AMP criteria for eight of the sarcomeric genes (MYH7, MYBPC3, TNNI3, TNNT2, TPM1, ACTC1, MYL2, and MYL3), providing a refined framework for variant interpretation in these genes." (PMID 41357762, 2025). "Furthermore, mutations in genes like TTN, TNNI3, and TNNT2 have been associated with a spectrum of cardiomyopathies, reflecting the complexity of genetic influences on cardiac function and structure." (PMID 38893676, 2024). "Mutations in TNNC1, TNNI3, and TNNT2 have been identified as relatively uncommon causes of cardiomyopathy, such as DCM, HCM, and RCM, when compared with the frequency of mutations in other sarcomere genes, probably because most of them are not compatible with life." (PMID 39211905, 2024). "These genes are associated with cardiomyopathy, familial hypertrophic, 4, or CMH4 (OMIM #115197) for MYBPC3, CMH1 (OMIM #192600) for MYH7, CMH3 (OMIM #115196) for TPM1, CMH2 (OMIM #115195) for TNNT2, and CMH7 (OMIM #613690) for TNNI3." (PMID 36555486, 2022). "Additionally, fewer cardiomyopathy-associated pathogenic mutations have been identified in TNNC1 compared to other thin filament genes, such as TNNT2 and TNNI3." (PMID 36158814, 2022). "Deletion of thin filament markers Tnnt2 and Tnni3 and thick filament marker Ttn in mice caused severe cardiomyopathy pinpointing the relevance that RYBP may function in the development of cardiomyopathy in humans as well." (PMID 32673370, 2020). "Notably, sarcomeric genes such as TNNI3, TNNT2, MYBPC3, and MYH7 are classically associated with HCM, but the findings obtained by the present review demonstrate their significant role in DCM as well, establishing them as shared genetic substrates between the two cardiomyopathies." (PMID 41374444, 2025). "We also found several VUSs in all four patients, including variants in genes whose loss of function is a known mechanism of cardiomyopathies, such as ANKRD1 and TNNI3, but whose role in skeletal muscle has not yet been fully described." (PMID 39063061, 2024). "Discordant interpretations exist for 229 variations in Hypertrophic Cardiomyopathy, with the majority of these variations located in well-known cardiomyopathy-related genes such as MYBPC3 (68 variations), MYH7 (49 variations), TNNI3 (20 variations), or TNNT2 (20 variations)." (PMID 37946154, 2023).
hypertrophic cardiomyopathy (49 papers, 2011 to 2025). "Pathogenic variants in TNNI3 (* 191044) are described in patients affected by hypertrophic cardiomyopathy." (PMID 39063061, 2024). "Pathogenic variants in genes such as MYH7, TPM1, and TNNI3 that encode parts of the cardiac sarcomere cause muscle diseases that affect the heart, such as dilated cardiomyopathy and hypertrophic cardiomyopathy." (PMID 37457373, 2023). "Cardiac troponin I (TNNI3) gene mutations account for 3% of hypertrophic cardiomyopathy and carriers have a heterogeneous phenotype, with increased risk of sudden cardiac death (SCD)." (PMID 32885985, 2020). "As the data are often population specific, we investigated the prevalence of TNNI3 mutations in 101 hypertrophic cardiomyopathy patients from southern India." (PMID 22876777, 2012). "About 2–7% mutations in TNNI3 have been reported to be associated with hypertrophic cardiomyopathy patients from various populations." (PMID 22876777, 2012). "TNNI3 is a gene that causes hypertrophic cardiomyopathy (HCM)." (PMID 38548731, 2024). "TNNI3 belongs to the sarcomere gene and is well-acknowledged to play a critical role in the development of ventricular hypertrophy and is a causative factor for hypertrophic cardiomyopathy." (PMID 35602610, 2022). "Further analysis, of the genes affected within the hypertrophic cardiomyopathy ontology, identified many structural genes including troponin I (Tnni3), troponin T (Tnnt2), troponin C (Tnnc1), α-actin C1 (Actc1) that are important for proper cardiac function." (PMID 24475304, 2014). "Analysis of a more specific ontology, cardiac hypertrophy – NF-AT signaling, revealed similar genes as the general hypertrophic cardiomyopathy ontology such as Myh6, Myh7, Tnnt2, Tnni3, and Actc1." (PMID 24475304, 2014). "We have sequenced all the exons, including the exon-intron boundaries of TNNI3 gene in 101 hypertrophic cardiomyopathy patients (HCM), along with 160 healthy controls, inhabited in the same geographical region of southern India." (PMID 22876777, 2012). "Here we investigated burst-like transcription and its consequences in cardiac tissue from Hypertrophic Cardiomyopathy (HCM) patients with heterozygous mutations in the sarcomeric proteins cardiac myosin binding protein C (cMyBP-C, MYBPC3) and cardiac troponin I (cTnI, TNNI3)." (PMID 36082122, 2022). "To this end, we conducted gene enrichment analysis, and observed stronger enrichments of upregulated genes involved in hypertrophic cardiomyopathy (ADRA1A, TNNI3, MYL2) and cardiac muscle contraction (CACNA1C, CASQ2, CAMK2B)." (PMID 37084237, 2023). "Next, our KEGG analysis showed that transcripts up-regulated in the mutant cardiomyocytes were related to hypertrophic cardiomyopathy (ACTC1, MYL2, MYL3), Ca2+-dynamics regulatory pathway (ATP2B4, CACNA1C, CAMK2B, PLN), as well as cardiac-muscle contraction transcripts (ACTC1, MYH7, TNNI3, TNNT2)." (PMID 35784482, 2022).
ischemia (48 papers, 2008 to 2025). A hypoperfusion of the BLOOD through an organ or tissue caused by a PATHOLOGIC CONSTRICTION or obstruction of its BLOOD VESSELS, or an absence of BLOOD CIRCULATION. "Other studies showed that altered function of TNNI3 due to either ischemia or depletion of TNNI3 can produce diastolic dysfunction and myocardial hypertrophy." (PMID 29438398, 2018).
Arrhythmia (41 papers, 2007 to 2026). Any cardiac rhythm other than the normal sinus rhythm. "We found the TNNI3 variant to be associated with myofibrillary derangement, which is often found to indirectly alter calcium homeostasis and engender cardiac arrhythmias." (PMID 34930847, 2021).
atrial fibrillation (33 papers, 2013 to 2025). A disorder characterized by an electrocardiographic finding of a supraventricular arrhythmia characterized by the replacement of consistent P waves by rapid oscillations or fibrillatory waves that vary in size, shape and timing and are accompanied by an irregular ventricular response. "TNNI3 p.R186Q mutation was previously reported in multiple families with HCM and a large Chinese family with co-segregated HCM and atrial fibrillation (AF)." (PMID 36818426, 2023).
cardiac hypertrophy (33 papers, 2011 to 2025). "Our interpretation is that mutation (p.Arg145Gly) in the gene encoding TNNI3 is delayed or subclinical cardiac hypertrophy until middle age or old age; this result indicates that genetic testing has an important diagnostic value, especially for clinically equivocal patient." (PMID 26199943, 2015).